PTX3 (pentraxin 3)
Diseases named in the same sentence as PTX3 in open-access papers (continued):
Sharing a sentence is not in itself a finding about the gene and the disease.
infection (continued). "Consequently, the enhanced expression of CCL2/MCP1, PTX3 and TNFα observed after infection with D26 could indicate a heightened disease risk from an NF-kB-driven inflammatory response by an ORF6 deletion variant." (PMID 33399033, 2021). "Because PTX3 is an important molecule of the innate immunity response, protecting against pathogens, its increase might even reflect an underlying, currently unknown, cause of IRDs, such as an ongoing infection." (PMID 28225768, 2017). "Upon re-infection, healed PTX3-/- mice produced significantly more IL-17A, while levels of IFN-γ, TNF-α, and IL-10 were similar." (PMID 41743710, 2026). "Overall, PTX3 plays a significant role in anti-infection by enhancing pathogen recognition, facilitating pathogen uptake by phagocytes, and activating complement cascades." (PMID 41479916, 2025). "PTX3 is produced locally at the site of infection and inflammation by a variety of cell types including fibroblasts, endothelial cells, mononuclear phagocytes, and DCs in response to pro-inflammatory signals such as TNF-α, IL-1β, Toll-like receptor agonist." (PMID 40646589, 2025). "PTX3 is primarily produced by monocytes and macrophages, and its levels significantly increase in response to infection and inflammation." (PMID 39878524, 2025). "In our cohort PTX3 correlated positively with peripheral Leishmania load, suggesting that PTX3 levels reflect active infection." (PMID 41471254, 2025). "Acute-phase proteins such as SAA3, M-SAA3.2, HP, and PTX3 are also upregulated, reflecting the localized expression of systemic responses to infection and tissue damage." (PMID 41156687, 2025). "As an integral part of innate immunity, PTX3 functions as a double-edged sword in infection and inflammation." (PMID 41479916, 2025). "Acute-phase inflammatory mediator pentraxin 3 (PTX3) is formed at the infection site and can be tested within a few hours." (PMID 39294659, 2024). "Given the role of PTX3 in humoral innate immunity against diverse microbial agents, we tested its role in resistance to infection with S. enterica serovar Typhimurium, which spreads from the gastrointestinal tract via the lymphatic route." (PMID 39640269, 2024). "The expression of PTX3 is triggered by infection, tissue damage, and dysmetabolism as part of the innate immune response." (PMID 39348530, 2024). "PTX3, a member of the long pentraxin family, is rapidly produced by phagocytes and stromal cells at sites of inflammation in response to infection or tissue injury." (PMID 39911783, 2024). "Our results show that plasma levels for PTX3, sMR and, to a lesser extent, C1-INH and C1s/C1-INH, measured soon after infection or symptom onset, are associated with disease severity." (PMID 39027374, 2024). "As opposed to this, the plasmatic concentration of IL-10 was not affected by the disease status, consistent with the view that this cytokine is synthesized and secreted locally (at sites of infection), as proposed for PTX3." (PMID 38790226, 2024). "PTX-3, a biomarker belonging to the pentraxin protein family, plays a crucial role in the acute phase response to inflammation and infection." (PMID 39201697, 2024). "PTX3 is known to play key roles in various pathological states, including infection, inflammation, and tissue damage." (PMID 39594709, 2024). "A defective control of bacterial load, associated with a higher mortality rate, was observed during the invasive phase of the infection, and PTX3 administration rescued the phenotype." (PMID 37222419, 2023). "(B) Area of inflammatory cells foci measured in lungs collected 18 and 36 hr post-infection from WT and Ptx3−/− mice." (PMID 37222419, 2023). "The structural complexity of the PTX3 protein perhaps explains the rather vast spectrum of interactions and functions of this pentraxin, which ranges from infection immunity to regulation of inflammation, tissue remodeling and cancer." (PMID 37885881, 2023).
infection (continued). "(A, B) Immunohistochemical analysis and quantification of PTX3 expression in lung sections (magnification 20x) from uninfected mice and mice sacrificed 6, 12, and 24 hr post-infection (n = 3–6)." (PMID 37222419, 2023). "Similar activations mediated by the exogenous PTX3 were also observed on the IL-6 levels that the air pouch exudates after 5 h of HA9801 infection." (PMID 36977278, 2023). "(E) Neutrophil number determined by flow cytometry in the BAL and lung collected 18 hr post-infection from WT mice treated intranasally 12 hr post-infection with recombinant PTX3 or PBS (data pooled from two independent experiments, n = 11–18)." (PMID 37222419, 2023). "In this study, we found that the transcription of gene PTX3 was significantly upregulated (more than a 30-fold change) by the infection of SS2 strain HA9801 on Raw264.7 and Hep2 cells." (PMID 36977278, 2023). "(B) Correlation between PTX3 and IL-1β protein levels in lung homogenates of all infected mice sacrificed from 2 to 48 hr post-infection (data pooled from five independent experiments, n = 60); Pearson correlation coefficient is reported." (PMID 37222419, 2023). "(D) Bacterial load in lungs collected 36 hr post-infection from WT and Selp−/− mice treated intranasally 12 hr post-infection with 1 μg/30 μl of recombinant PTX3 or phosphate-buffered saline (PBS) (data pooled from two independent experiments, n = 10–11)." (PMID 37222419, 2023). "By contrast, even though these mice presented lower amount of neutrophils recruited in response to the infection, they expressed the same pulmonary levels of PTX3 as WT mice." (PMID 37222419, 2023). "The primary objective of this study was to assess pentraxin-3 as a biomarker of DFU infection, limb amputation level prognosis, and patient survival." (PMID 37510110, 2023). "Among conserved fluid-phase PRMs, Pentraxin 3 (PTX3), is a member of the pentraxin family characterized by multifunctional properties, including regulation of innate immunity during infections." (PMID 37222419, 2023). "As early as 6 hr post-infection, we detected a local expression of PTX3 in the alveolar compartment near the pulmonary veins." (PMID 37222419, 2023). "Mice infected with PTX3-opsonized S. pneumoniae serotype 3 showed the same local bacterial burden at 6–36 hr after infection as mice infected with pneumococcus incubated with PBS." (PMID 37222419, 2023). "(C) Inflammatory histological score measured in lungs collected 18 and 36 hr post-infection from WT and Ptx3−/− mice." (PMID 37222419, 2023). "All our findings suggested that S. suis surface CPS2 and host PTX3 proteins coordinately regulate the host’s inflammatory response during the infection of SS2." (PMID 36977278, 2023). "At 12 hr post-infection, we were able to detect PTX3-specific staining in endothelial cells in the area where we can appreciate inflammatory cells infiltration." (PMID 37222419, 2023). "PTX3 protein levels determined by ELISA in lung homogenates (C) and serum (D) collected 36 hr post-infection in WT, Il1r−/− and Myd88−/− mice (n = 7–8)." (PMID 37222419, 2023). "In fact, when mice were infected with S. pneumoniae serotype 1, we observed a strong PTX3 production during the invasive phase of the infection and a correlation with IL-1β levels." (PMID 37222419, 2023). "(C) Survival of WT and Ptx3−/− mice (data pooled from two independent experiments, n = 18) was monitored every 6 hr after infection with 5 × 103 CFU." (PMID 37222419, 2023). "The present study has described the possible value of the IL-1 and TNF- α driven PTX3 as a CSF biomarker for infections in the CNS." (PMID 36862691, 2023). "Bacterial load in lungs (G) and spleens (H) collected 36 hr post-infection from WT, Ptx3−/−, Selp−/−, and Ptx3−/−Selp−/− mice (data pooled from two independent experiments, n = 8–12)." (PMID 37222419, 2023).
infection (continued). "(D) Neutrophil number determined by flow cytometry in BAL and lungs collected 18 hr post-infection from WT and Ptx3−/− mice (data pooled from two independent experiments, n = 11–18)." (PMID 37222419, 2023). "BAL and lungs from WT and Ptx3−/− mice were collected 24 hr after infection with a lethal inoculum of S. pneumoniae (data pooled from two independent experiments, n = 9–14)." (PMID 37222419, 2023). "Upregulated plasma PTX3 levels have been demonstrated in cardiovascular diseases, cancer, and infections." (PMID 35676730, 2022). "The binding activities of PTX3 allow for a multitude of functions with infection control, immune modulation and complement activation." (PMID 35704081, 2022). "After 5 days of hospitalization, a general decrease of PTX3 circulating levels was observed, in parallel with an improvement of patients’ conditions and a reduction of the inflammation and/or infection burden." (PMID 36189302, 2022). "Many studies have found that the expression of PTX3 increased after infection with Pseudomonas aeruginosa or Neisseria meningitidis." (PMID 36059501, 2022). "PTX3 is involved in innate resistance against pathogens, mainly acting at the infection and inflammation sites." (PMID 36611613, 2022). "These markers returned to levels comparable to controls after one week, except PTX-3 that remained elevated in patients with Delta infection after one week, and GDF-15 that remained elevated in both groups." (PMID 36159859, 2022). "The long pentraxin PTX3 is a crucial component of humoral innate immunity produced at inflammatory sites in response to infection or tissue injury." (PMID 36362273, 2022). "In healthy individuals, PTX3 is barely detectable in blood circulation, whereas its serum level strongly increases within 6–8 h of inflammation and infection." (PMID 36499628, 2022). "For its actions, PTX3 can be considered a humoral pattern recognition molecule that provides defence against infection playing several function in tissue repair." (PMID 36287942, 2022). "Pentraxin 3 (PTX3) serves a role in protection against infection, inflammation control, and matrix deposition and has been proven as a biomarker of inflammatory status." (PMID 34035808, 2021). "Recombinant mouse PTX3 (mPTX3) was administered at the time of infection and 24 h later in wild-type and Ptx3-/- mice." (PMID 34093560, 2021). "Our study was performed to elucidate the actual role of PTX3 in this infection and its mechanisms of action." (PMID 34093560, 2021). "We concluded that there is a statistically significant difference in PTX3 levels in umbilical cord blood in newborns with infection as compared to healthy ones." (PMID 34307663, 2021). "PTX3-dependent regulation of inflammation and tissue damage were found the major mechanisms responsible of the outcome of the infection." (PMID 34093560, 2021). "While studying the impact of PROM on PTX3 level, the authors found the highest marker levels in neonates with both infection and PROM." (PMID 34307663, 2021). "Soluble forms of pattern recognition molecule PTX3 are critical for recognition of conserved molecular patterns present in pathogens, thereby building innate immunity against infection." (PMID 33925033, 2021). "The comparison of susceptibility of wild-type, Ptx3-/-, C3-/- and Ptx3-/-/C3-/- mice to the infection showed that PTX3 acted in a complement-independent manner." (PMID 34093560, 2021). "We observed an increase of the concentration of IL-1β, TNF-α and MPO during the progression of the infection, which positively correlated with the concentration of PTX3 (P < 0.0001, P = 0.0018, P = 0.0139, respectively)." (PMID 34093560, 2021). "Pentraxin-3 plays an important role in innate humoral immune response, inflammatory response, anti-infection, as well as tissue damage and repair." (PMID 34001041, 2021).
infection (continued). "In vascular endothelium and smooth muscle cells, pro-inflammatory signals including IL-1β, LPS, oxidized LDL, and the products of their degradation stimulate pentraxin-3 synthesis and production at the site of infection." (PMID 35387000, 2021). "Currently, persistent studies have acknowledged that PTX3 plays an indispensable role in immunity, inflammation, infection, tissue remodeling and fertility." (PMID 33746606, 2021). "During the first 12 hours of life, PTX3 concentration was significantly higher in newborns with infection as compared to healthy ones (p = 0.01)." (PMID 34307663, 2021). "With this schedule of treatment, we observed a better control of the infection in Ptx3-/- mice, since PTX3 treatment abolished the difference in spleen CFUs between Ptx3-/- and wild-type mice." (PMID 34093560, 2021). "The results obtained demonstrate a clear involvement of PTX3 in the control of the infection, in terms of bacterial load, mortality and inflammation." (PMID 34093560, 2021). "The long PTX3 is a soluble pattern recognition molecule produced by somatic and immune cells at the site of infection." (PMID 34867977, 2021). "There were statistically significant differences in PTX3 values in umbilical cord blood between healthy newborns and those with the infection (p = 0.02)." (PMID 34307663, 2021). "Early (18 h) after intranasal infection, lung and blood bacterial loads were comparable in Ptx3+/+ and Ptx3-/- mice." (PMID 34093560, 2021). "The receiver operating characteristic curve for serum PTX3 level of 8571 pg/mL presents a moderate sensitivity (39.3%) and high specificity (95.5%) in the early prognosis of infection in the study group." (PMID 34307663, 2021). "Previously, PTX3 was shown to be protective in models of tissue injury mediated by infection, LPS treatment, and sterile inflammation." (PMID 32938460, 2020). "The pathophysiological roles of PTX3 have been widely investigated using genetically modified mice in various diseases, including infection, tissue injury, and cancer." (PMID 32938460, 2020). "Monitoring the level of PTX3 has not only been described to be a good biomarker for detecting infections, but also to follow the response to therapy." (PMID 31031772, 2019). "In the serious infection group, all cases exhibited a high concentration of PTX3 (462.1 ± 266.6 ng/mL)." (PMID 31147578, 2019). "PTX3 expression in splenic tissue correlates significantly with the bacterial burden in the same tissue samples, which makes PTX3 a valuable indicator of infection severity." (PMID 30774632, 2019). "Cardiovascular diseases, cancer and infections, all characterized by an inflammatory origin, are the most relevant pathologies showing upregulated plasma PTX3 levels." (PMID 31031772, 2019). "Since RNA-seq data had shown a consistent PTX3 up-regulation in a variety of infections, but with distinct regulation patterns, we next analyzed the PTX3 response to a more general inducer of inflammation." (PMID 30774632, 2019). "The homology with CRP, that was first discovered in the serum of patients with acute pneumococcal pneumonia and is upregulated in the context of inflammation and infections, prompted investigations on the involvement of PTX3 as biomarker of infections." (PMID 31031772, 2019). "Preclinical data in the mouse and the homology with CRP, a molecule used to monitor inflammatory diseases and infection in clinical practice, prompted investigation of PTX3 as possible marker of human pathology." (PMID 31057548, 2019). "This notable, time-dependent, induction in monocyte PTX3 expression during Bm or Bt infection was validated by qPCR as up- or down-regulated, albeit with magnitudes different from those recorded by microarray analysis." (PMID 31492148, 2019). "Inflammation, however, induces a stimulus- and infection dose-dependent PTX3 response in spleen and other tissues on mRNA level." (PMID 30774632, 2019).
infection (continued). "Long pentraxin 3 (PTX3) is a soluble pattern recognition receptor produced by a variety of cells at the site of infection or inflammation." (PMID 31437159, 2019). "The interaction between PTX3, fibrin and plasminogen is potentially relevant during specific infections or in septic conditions, but further studies are needed to address this aspect." (PMID 31031772, 2019). "The pentraxin PTX3, which is produced by several innate immunity cell types, plays essential roles in the innate immune defense against infections." (PMID 30045763, 2018). "In a murine model of allogeneic bone marrow transplantation, PTX3 treatment induced complete resistance to infection and reinfection with invasive aspergillosis." (PMID 29492210, 2018). "Infection of Myd88-/- BMDCs significantly reduced the release of PTX3 with respect to wild-type BMDCs." (PMID 30532257, 2018). "As oppose to the protective effect of recombinant PTX3 Ptx3-/- infected mice showed a defective ability to clear bacteria and an accelerated kinetics of death in the same infection model." (PMID 30532257, 2018). "Elevation of PTX3 levels in the circulation following infection or tissue damage appears to predict poor patient outcome, as seen in patients with sepsis and acute lung injury." (PMID 29492210, 2018). "Lastly, it would have been interesting to have local PTX3 measurements from the focus of infection and compare this with the released amount in the blood stream." (PMID 26880104, 2016). "Our data show that infection was accompanied by the up-regulation of c1qa and ptx3 as well as the down-regulation of mbl2." (PMID 27100179, 2016). "This population includes several neutrophil-associated genes (OLFM4, CD177, SERPINB1, S100P, PTX3 and MMP8), suggesting that there is an accumulation of neutrophils in PBCMs during the course of infection." (PMID 27595844, 2016). "Using a peritoneal exudate model, we demonstrated increased recruitment of neutrophils and inflammatory monocytes in PTX3-/- mice during early stages of infection." (PMID 25695775, 2015). "Pentraxin 3 (PTX3), the prototype long pentraxin, is an acute phase protein which can be produced by a variety of cells at the site of infection or inflammation." (PMID 26644796, 2015). "PTX3 was administered at the moment of ip infection with live bacteria (4x104 ip) and animals were sacrificed 18 hours after the challenge to evaluate blood CFU." (PMID 25786110, 2015). "PTX3 is an acute-phase protein that is produced by a variety of tissue cells at the site of infection or inflammation." (PMID 26174362, 2015). "The exact role of PTX3 in WNV-infection remains to be elucidated, but our results suggest a potential antiviral role in some species, notably rabbit." (PMID 26697438, 2015). "Together, these results suggest that acute production of PTX3 dampens early recruitment of neutrophils and inflammatory monocytes, but enhances the egress of inflammatory monocytes in the latter stages of infection." (PMID 25695775, 2015). "At 24 hpi, RRV infection of WT fibroblasts resulted in significant up-regulation of PTX3 mRNA expression compared to mock-infected WT fibroblasts." (PMID 25695775, 2015). "Here we report that PTX3 binds MenB, recognizes selected recombinant surface proteins from MenB, and has protective activity against infection in vivo." (PMID 25786110, 2015). "Intracellular PTX3 migrates from perinuclear space to cytoplasm during infection and PTX3 co-localized with RRV in the cytoplasmic space suggests the possibility of intracellular associations between PTX3 and RRV." (PMID 25695775, 2015). "By means of this model we found that PTX3 administration can reduce infection burden in infant rats challenged ip with Nm, suggesting that this molecule can exert a protective effect in vivo." (PMID 25786110, 2015). "Pentraxin 3 (PTX3) is an acute-phase inflammatory mediator produced at the site of infection that can be assayed in a few hours." (PMID 25314919, 2014).